IL6 (interleukin 6)
Diseases named in the same sentence as IL6 in open-access papers (continued):
Sharing a sentence is not in itself a finding about the gene and the disease.
COVID-19 (continued). "In line with this emerging understanding of the complex and multifactorial pathophysiology of COVID-19, we found that, unlike the levels of CRP and IL-6, IP-10 levels are associated with disease severity and reflect the patient’s response to corticosteroids." (PMID 33434221, 2021). "In our study, we confirmed higher levels of inflammatory markers—C-reactive protein and IL-6—in critically ill COVID-19 patients compared to non-ICU COVID-19 patients." (PMID 34071149, 2021). "Our meta-analysis revealed significantly lower levels of immune cells (CD3+ T, CD4+ T, CD8+ T, B and NK cells), higher levels of cytokines (TNF-α, IL-5, IL-6 and IL-10) and higher levels of chemokines (MCP-1, IP-10 and eotaxin) in severe cases in comparison to mild cases of COVID-19." (PMID 34344353, 2021). "TNF-α, MCP-1 and IP-10 (but not IL-6 or IL-8) were significantly higher in both COVID-19 groups than the control group." (PMID 33921604, 2021). "In terms of laboratory findings, an increased erythrocyte sedimentation rate (ESR) and elevated levels of C-reactive protein (CRP), lactate dehydrogenase (LDH), ferritin, interleukin 6 (IL-6), and tumor necrosis factor-α (TNF-α) are commonly observed in patients with COVID-19." (PMID 34295915, 2021). "Recent studies found that T cells counts were negatively correlated to IL-6, IL-10 and TNF-α concentration in serum, which indicated that these cytokines may be involved in T cells depletion in COVID-19 patients." (PMID 34578457, 2021). "Notably, out of 27 differentially expressed proteins, 15 were found to be regulated by IL-1β, IL-6, or tumor necrosis factor (TNF), which are seen at markedly higher levels in most severe COVID-19 patients." (PMID 34667241, 2021). "It was expected that 97.9% of patients with IL-6 levels lower than 51.75 pg/mL would not die by COVID-19." (PMID 33809913, 2021). "IL-6 expression was not elevated; high levels of IFN and IL-6 have been associated with severe COVID-19." (PMID 34010360, 2021). "reviewed inflammatory markers in over 3900 COVID-19 patients and found that survivors had a lower level of IL-6 compared with nonsurvivors." (PMID 33741059, 2021). "To investigate the role of cytokines and chemokines in the inflammatory status of COVID-19 and MIS-C, we measured plasma levels of IL-1ß, IL-2, IL-4, IL-5, IL-6, IL-10, TNF-α, IL-17A, IFN-α, IFN-γ, CXCL10/IP-10, CXCL8/IL-8, CXCL9/MIG, CCL5/RANTES, and CCL2/MCP1." (PMID 33841438, 2021). "While IL6 levels were not significantly higher in the COVID-19 cohort, as previous studies have found they trended higher in men." (PMID 34838058, 2021). "In particular, mild COVID-19 is characterized by increase of IFN-α, IFN-γ, IL6, IL10, IL1RA [TE87, TE88, TE89], while severe disease is characterized by a downregulation of IFNα, and a parallel up-regulation of IFN-β, IFN-γ, IL6, TNF, IL10, CCL7 [TE89, TE90, TE94]." (PMID 34876157, 2021). "People living with HIV with suppressed viral loads who are hospitalized with COVID-19 have similar levels of CRP, IL-6, ferritin and neutrophil counts as HIV-negative individuals, though these laboratory values were lower in people living with HIV without suppressed viral loads." (PMID 34567235, 2021). "A recent systematic review and meta-analysis concluded that threefold higher serum IL-6 levels were found in patients with severe COVID-19 compared with those with noncomplicated disease." (PMID 34422145, 2021). "With our results, we confirm observations made by other groups showing that IL-6 allows distinguishing between severe and nonsevere COVID-19." (PMID 34372587, 2021). "We have observed that the proportion of diabetes in patients with mild and severe cases with COVID-19 (MS and SCS group) was higher than that of AS group, and the concentration of IL6, IL8 and IL10 in MS and SCS groups was higher than that of AS group (P < 0.05)." (PMID 34118952, 2021).
COVID-19 (continued). "In fact, anti-IL6 monoclonal antibodies tocilizumab (already approved for the treatment of CAR T cell-induced cytokine release syndrome), siltuximab and sarilumab are currently being studied in the management of severe COVID-19." (PMID 34829918, 2021). "However, studies showed that these patients with COVID-19 present a high expression of tumor necrosis factor (TNF)-α, interleukin (IL)-1β, and IL-6." (PMID 33776796, 2021). "The administration of the IL-6 inhibitor, tocilizumab, to mitigate the cytokine storm has been reported to promote candidemia among severely ill COVID-19 patients; however, none of our patients received this medication." (PMID 33917967, 2021). "Particularly IL-6 was found to play a role in the pathophysiology of acute kidney injury in earlier studies and may contribute to AKI in COVID-19 as well." (PMID 34110585, 2021). "In addition to monoclonal antibodies targeting IL-6, JAK inhibitors have been tested in several clinical trials on patients with COVID-19 (clinicaltrials.gov)." (PMID 33995078, 2021). "COVID-19 is characterized by increased levels of numerous cytokines, mainly of proinflammatory character, including tumor necrosis factor-alpha (TNF-alpha), interleukin-6 (IL-6), and CRP." (PMID 34946334, 2021). "Moreover, IL-6 and TNF-α levels have been shown to predict disease severity, clinical progression, and death in hospitalized COVID-19 patients." (PMID 34593760, 2021). "Our study indicated that several compounds such as quercetin, UA, luteolin, and rutin could decrease IL-6 expression, showing an anti-CRS effect in COVID-19 patients." (PMID 33146673, 2021). "Ferritin and IL-6 are significant biomarkers of CSS, and increases in levels of either could be considered red flags of systemic inflammation and poor prognosis in COVID-19, especially in the oldest patients and those with comorbidities." (PMID 34185801, 2021). "However, certain inflammatory/SASP factors released by senescent human lung cell types—including IL-1α, IL-1β, IL-6, MCP-1, TNFα, and MMP-1—are central to the pathological cytokine storm seen in some COVID-19 patients." (PMID 34103349, 2021). "In addition, the levels of IL-6 and IL-10 in SCS COVID-19 patients were significantly higher than that in AS and MS group." (PMID 34118952, 2021). "IL-6, CXCL10, CXCL9, CCL2, IL1-Ra, IL-10, G-CSF and TNF-α were the cytokines with the highest contribution to dimension 2 in the PCA and were significantly increased in acute COVID-19 patients in comparison to HC." (PMID 34572439, 2021). "Moreover, cytokines such as IL-6, IL-10, and TNF-α were revealed to increase with the severity of the diseases in COVID-19 patients." (PMID 33557779, 2021). "These MAbs may play a vital role in reducing IL6 level and reduce instances of ARDS in COVID-19 patients." (PMID 33664772, 2021). "High plasma levels of tumor necrosis factor-α (TNF-α), IL-1β, IL-6, and IL-8 have been confirmed in COVID-19, especially in non-survivors and in critically ill patients." (PMID 34177896, 2021). "Based on ROC analysis, nine biomarkers (TNF-α, IL-10, MIG, IL-6, IP-10, M-CSF, G-CSF, GM-CSF, IFN-α2) were established as good early predictors for COVID-19 patients who may require ICU admission." (PMID 34858428, 2021). "Higher values of CRP, ESR, IL-6, and β-2-glycoprotein antibodies as well as higher frequencies of CRP elevation and any Ig decrease were observed for post-COVID-19 patients compared to healthy controls (p = 0.009; p = 0.007; p = 0.004; p = 0.031; p = 0.007; p = 0.015, respectively)." (PMID 34722682, 2021).
COVID-19 (continued). "Among cytokines, IL-6 and TNF-α levels at the time of hospitalization were reported to be independent predictors of disease severity and death in hospitalized patients with COVID-19." (PMID 34769508, 2021). "Our results demonstrate that increasing the levels of IL-6 correlate to disease severity and identifying particularly well those patients who evolved to more severe stages of COVID-19, a pattern not observed with other markers such as CRP." (PMID 33679753, 2021). "Based on our mathematical approach to identify relevant parameters, we selected five patient-discriminatory proteins (ADM, IL-6, MCP-3, TRAIL-R2, PD-L1) that were predictive for COVID-19 rule-in and/or hospitalization and at least for one of the following events: ICU treatment, TE, MV, and death." (PMID 34960725, 2021). "Moreover, plasma levels of IL-6, IL-8, and TNF-α peaked before death as demonstrated in autopsies of COVID-19 patients." (PMID 34367380, 2021). "Pooled results from twenty-two studies of both severe and non-severe cases revealed higher levels of Il-6 in patients with severe COVID-19 in comparison to the group of mild COVID-19 cases [MD 28.99; 95% CI 18.24 to 39.75; N = 4,861]." (PMID 34185801, 2021). "High IL-6 and SARS-CoV-2 RNAaemia may reflect pathophysiologic evidence of future deterioration of COVID-19, including hyperinflammation and viral overload, thereby helping us to decide therapeutic strategy." (PMID 34379684, 2021). "Compared to those with non-severe COVID-19, patients with severe COVID-19 had significantly higher circulating levels of neutrophil-to-lymphocyte ratio, C-reactive protein, procalcitonin, D-dimer, IL-6 and IL-10 both in MAFLD and in non-MAFLD patients." (PMID 33763027, 2021). "However, in relation to the group mild B COVID-19 subgroup, it is possible to highlight other significant positive correlations between IL-37 and the cytokines IFN-α, IFN-γ, IL-6, and IL-10." (PMID 33717074, 2021). "The reduction is particularly marked in severe COVID-19 cases, and a strong negative correlation is seen between T-cell counts and IL-6, IL-10, and TNF-α concentrations." (PMID 34940403, 2021). "Interestingly, PD COVID-19 patients had statistically significant higher peak WBC counts and higher creatinine kinase, ferritin, LDH, lactate, ALT, AST, and IL-6 levels upon admission (base) compared to HD COVID-19 patients." (PMID 34293004, 2021). "COVID-19 patients with headache had significantly higher serum levels of HMGB1, NLRP3, ACE2, and IL-6 than COVID-19 patients without headache, whereas CGRP and IL-10 levels were similar." (PMID 34794375, 2021). "Levels of IL-6, CRP, absolute lymphocyte count, neutrophils and neutrophil-to-lymphocyte ratio obtained upon admission may help predict the severity of COVID-19." (PMID 34567235, 2021). "Given the key role of IL6 in SARS-CoV-2 pathogenesis, blocking IL6 signaling may prevent hyperinflammation and increase survival in COVID-19 patients." (PMID 34975885, 2021). "Unlike other states where cytokine levels are increased, as in sepsis, the levels of IL-6 and TNF-α in patients with COVID-19 were sustained during days or even weeks, which makes the decision for administering the anticytokine treatment on time more difficult." (PMID 33968298, 2021). "In addition, symptomatic COVID-19 mothers had statistically significant elevated levels of 4 of the 10 inflammatory markers (IFN-γ, IL-4, IL-6, and IL-12) compared to asymptomatic COVID-19 mothers." (PMID 34382820, 2021). "Our data demonstrated strong enrichment of CCL2/19/20, CXCL10, GM-CSF, IL-6/8/15, S100A9, SCGF, TNF and TREM-1 in COVID-19, which could potentially play a critical role on the pathogenesis of the disease." (PMID 34238349, 2021). "Currently, multiple biomarkers in COVID-19 have been identified, such as leukocytes, C-reactive protein (CRP), procalcitonin (PCT), lactate dehydrogenase (LDH), ferritin, and cytokines (IL-2R, IL-6, IL-8, IL-10, and TNF-α)." (PMID 34573984, 2021).
COVID-19 (continued). "The hyperproduction of proinflammatory cytokines, such as IL-1, IL-6, IL-12, interferon γ (IFN-γ) and tumor necrosis factor α (TNF-α), which preferentially target the pulmonary tissue, seems to significantly worsen the prognosis of COVID-19 patients." (PMID 33916917, 2021). "Cytokine storm, hyperinflammation, multiorgan failure, and acute respiratory distress syndrome were described in COVID-19 patients with high fever, dyspnea, lymphopenia, and high serum ferritin, D-dimers, C-reactive protein (CRP), and cytokines, including IL-1b, IL-6, and TNF-α." (PMID 34578460, 2021). "A previous study revealed that plasma metabolites in tryptophan and K metabolism correlated with IL-6 abundance in a sex-aggregated cohort of COVID-19 patients, but sex specificity was not examined." (PMID 34230210, 2021). "Importantly, in COVID-19 patients requiring ICU admission, significantly higher numbers of IL-6 producing monocytes have been reported." (PMID 34539644, 2021). "Significantly upregulated genes were involved in “TNFα signaling via NF-κB”, “inflammatory responses”, and “cytokine-cytokine receptor interaction”, “IL6-JAK STAT3 signaling”, “coagulation”, “hypoxia”, which had been reported for COVID-19, while cell cycle-related pathways were downregulated." (PMID 34697287, 2021). "The COVID-19 patients had elevated troponin T level, abnormal echocardiography, decreased LVEF, and elevated IL-6 levels, which could indicate a possible ongoing cytokine storm." (PMID 33969006, 2021). "Multiple studies have reported a significant difference in the IL-6 levels between complicated and non-complicated COVID-19 cases." (PMID 34538093, 2021). "To ascertain if the therapeutic effect of Xanthohumol relieved virus-induced cytokine dysregulation, we determined the expression levels of IL-6, IL-10, and TNF-α, which are prognostic markers for severe COVID-19, as well as other major pro-inflammatory cytokines including IFN-γ." (PMID 34702802, 2021). "Our findings support the case for a net negative effect of IL-6 in COVID-19 as we demonstrate that DES, a downstream biomarker of tissue damage, associates with higher circulating IL-6." (PMID 35111793, 2021). "For example, higher levels of C-reactive protein and interleukin-6 were observed in COVID-19 patients with AF, compared to patients without AF." (PMID 34199857, 2021). "As IL-6 is important in COVID-19, TCZ has been used to treat COVID-19 patients clinically." (PMID 33907513, 2021). "Another study also reported that type I IFN responses were highly impaired in the peripheral blood of patients with severe or critical COVID-19, as indicated by low levels of type I IFNs and ISGs, despite increased levels of TNF-, IL-6-, and NFκB-driven inflammatory responses." (PMID 33953323, 2021). "We found significant direct correlations between galectin-3, CCL2, PON1, IL-6, IL-10, CRP, ACE2, and angiotensin II concentrations in COVID-19 positive patients as well as with aminotransferase activities and triglycerides, and inverse correlations with HDL-cholesterol." (PMID 34205807, 2021). "The efficacy of a therapy blocking IL-6 has not yet been broadly recognized, but one recent study showed that tocilizumab reduced disease progression in patients with COVID-19 not receiving mechanical ventilation." (PMID 33622974, 2021). "Although the paramount cytokine involved in the pathogenesis of COVID-19 has not been identified yet, interleukin-6 seems to be crucial." (PMID 34630377, 2021). "Lastly, since this study represents patients admitted during the earlier phases of COVID-19, treatment strategies did not include remdesivir, interleukin 6 (IL-6) antagonists, convalescent plasma, or dexamethasone, which are now commonly utilized." (PMID 34430159, 2021). "Moreover, we found a prompt decrease in serum CRP, IL-6, IP-10, MCP-1, and IFN-γ levels in severe patients with COVID-19 who responded well to tocilizumab." (PMID 34631752, 2021).
COVID-19 (continued). "Several reports have also observed higher concentrations of C-reactive protein, IL-6, IL-10, ferritin, leukocytes and lower lymphocyte percentage in severe COVID-19 patients compared to that of non-severe patients." (PMID 33995267, 2021). "Immunostaining of postmortem tissue from COVID-19 patients showed that in secondary lymph nodes, SARS-CoV-2 can infect ACE2-expressing resident CD169+ macrophages that, in turn, are stimulated to produce IL-6 levels." (PMID 34209845, 2021). "However, an early but transient inflammatory cytokine response with increased CXCL10, IFN-g, IP-10/, IL-6 and CRP was observed at day 2 and returned to baseline levels by day 8 following a COVID-19 vaccination with BNT162b2 mRNA (Pfizer/BioNtech)." (PMID 34835155, 2021). "COVID-19 positive individuals with diabetes have been shown to have significantly increased levels of IL-6 and C-reactive protein compared to COVID-19 patients without diabetes." (PMID 34444990, 2021). "By developing and validating our model, we also confirmed that certain inflammatory markers such as IL-6, D-dimer, NLR, and lactate dehydrogenase (LDH) could be used as predictors of COVID-19 disease severity." (PMID 35071229, 2021). "Currently, serum IL-6 level, along with other inflammatory markers such as CRP, ferritin, are used in isolation or together to determine and predict the efficacy of tocilizumab in COVID-19 treatment." (PMID 34001244, 2021). "The levels of short and medium chain acylcarnitines have been previously reported by as being reduced in COVID-19 patients versus controls irrespective of Interleukin 6 (IL6) levels." (PMID 34928464, 2021). "Some modeling studies have shown that levels of IL-6 and CRP could be used as independent factors to predict the COVID-19 severity." (PMID 34960790, 2021). "Additionally, DM, elevated levels of blood IL-6, LDH, and high lymphocyte count were more commonly seen in those who died of COVID-19 illness." (PMID 34828513, 2021). "Significant upregulation of tumor necrosis factor-α (TNF-α), interleukin-6 (IL-6), and C–C motif chemokine ligand 5 (CCL5) was observed from exposure of immortalized human hepatocytes (IHHs) to exosomes isolated from COVID-19 patient plasma compared with exosomes from healthy normal plasma." (PMID 33804769, 2021). "Total T cells, and CD4+ and CD8+ T cell counts are negatively correlated with serum IL-6, IL-10, and TNF-α levels in COVID-19 patients, and patients in the disease resolution period exhibit decreased IL-6, IL-10, and TNF-α concentrations and restored T cell counts." (PMID 34818337, 2021). "Inflammatory and coagulation markers such as C-reactive protein, interleukin-6, and D-dimer were elevated in patients with COVID-19; however, they were not routinely measured for patients with influenza, limiting any comparisons." (PMID 34307971, 2021). "In addition, the factors involved in pulmonary fibrosis such as TGF-β, interleukin-6 (IL-6), and tumor necrosis factor-α (TNF-α) were increased in patients infected with COVID-19." (PMID 35069217, 2021). "Furthermore, we examined mRNA expression of cytokines (IL-6, TNF-α, and CXCL10) which are known to be upregulated in COVID-19 patients." (PMID 34815389, 2021). "Then, the cytokines (including CRP, Ferritin, IL-6, TNF-α, GM-CSF, IP-10, and MCP1α/1β) in the serum of severe patients with COVID-19 were higher than that in the mild patients with COVID-19, while the number of T and NK cells decreased and the number of neutrophils increased." (PMID 34667157, 2021). "In this regard, the increase of blood inflammatory markers (e.g., CRP, IL-6, TNF-α, IL-1, etc.)in GBS tested cases may reinforce the hypothesis of a systemic inflammatory storm in COVID-19." (PMID 32840686, 2021). "Therefore, it is necessary to detect the levels of D-dimer and IL-6, TNF-α, and IL-1 to prevent and predict the intestinal coagulation disease of COVID-19." (PMID 34858386, 2021).